CDC42 (cell division cycle 42)
Diseases named in the same sentence as CDC42 in open-access papers (continued):
Sharing a sentence is not in itself a finding about the gene and the disease.
cancer (continued). "Cytoplasmic p120ctn was found to interact with Rho GTPases RhoA, Rac1 and Cdc42 to influence cancer cell motility and metastasis." (PMID 30795761, 2019). "Previous reports suggest that diverse Rho GTPases (CDC42, RhoA, Rac, RhoV, and RhoC) are activated in various types of cancer." (PMID 30717410, 2019). "Our attention was drawn to the large number of regulators of Rho-family GTPases such as Rac1, Rho, and Cdc42, known to be involved in the regulation of cell motility, and considered as interesting drug targets to prevent cancer dissemination." (PMID 30971775, 2019). "Multiple cancer-associated proteins, including several that have since been shown by others to regulate YAP or TAZ (RhoA, Cdc42, Ras, and phosphoinositide 3-kinase (PI3K)) (28, –, 32), increased YAP/TAZ transcriptional activity." (PMID 30559289, 2019). "In this model, Cdc42-mediated activation of MRCK is required to allow cancer cell migration behind leading fibroblasts." (PMID 30754684, 2019). "Despite the abundant study of Cdc42 in cancer cell proliferation, surprisingly little is known about the relationship between Cdc42 and cancer cell invasion under HG condition." (PMID 30621321, 2019). "Activated CDC42 (GTP bound CDC42) binds to the p85 subunit of PI3K leading to the activation of PI3K/Akt pathways in cancer." (PMID 30717410, 2019). "In this section, we will discuss the discovery, molecular structure, and function of Cdc42 inhibitors in cancer therapy." (PMID 29596304, 2018). "The data presented improve our understanding of the Cdc42–WASP interface and also add to the body of information available for Cdc42–effector complex formation, therapeutic targeting of which has promise for Ras-driven cancers." (PMID 30104412, 2018). "The Rho-GTPase Cdc42 was shown to similarly promote cancer cell transendothelial migration by regulating β1 integrin gene transcription through SRF-mediated activation." (PMID 29907768, 2018). "We will describe the expression and regulators of Cdc42 and discuss their downstream effectors in cancers." (PMID 29596304, 2018). "More recently, identification of point mutants in the Rho GTPases Rac1, RhoA, and Cdc42 in human tumors has finally given rise to a new paradigm, and we can now state with confidence that Rho GTPases serve as oncogenes in several human cancers." (PMID 30544828, 2018). "CDC42 was also chosen to be studied because it has a critical role in several metabolic pathways of cancer that leads to proliferation, migration and invasion." (PMID 30376837, 2018). "The Golgi apparatus has been linked to polarity; studies have illustrated that GM130 is a regulator of cdc42 signaling that regulates cell polarity and provides a potential link between Golgi and cancer initiation." (PMID 30504808, 2018). "The consequences of this interaction led to the migration of cancer cells due to polarization, accumulation of small GTPases, Rac, Cdc42, and PI3K at the leading edge, actin polymerization and F-actin formation." (PMID 29358632, 2018). "Regarding possible new treatments for cancer, miRNA and small molecules targeting Cdc42 and related pathways have been recently found to be effective on cancer." (PMID 29596304, 2018). "Fibroblasts, endothelial cells, and many types of cancer cells migrate in a mesenchymal mode that depends on Rac/CDC42 signaling and extracellular proteolysis." (PMID 29743635, 2018). "DLC1 is primarily involved in regulating the Rho GTPases (RhoA and Cdc42), which are involved in cancer-related signalling and are closely related to the occurrence and development of tumours." (PMID 29212270, 2017). "As an effector of CDC42, IQGAP1 can bind directly to CDC42 and has been implicated in the modulation of cell architecture and regulation of exocytosis in human cancers." (PMID 28282856, 2017). "CDC42, a member of the Rho GTPase family, has been reported to be overexpressed in several different cancers, including HBV-related HCC." (PMID 28282856, 2017).
cancer (continued). "Altogether, we show that CDC42 has an active oncogenic role in CRC via the transcriptional regulation of multiple cancer-related pathways and that CDC42-mediated silencing of CACNA2D2 is clinically relevant." (PMID 28460460, 2017). "It was shown previously that inhibition of CDC42 can decrease cancer cell proliferation and that metformin can inhibit cell proliferation." (PMID 28423712, 2017). "For example, miR-18a impairs cancer cell growth via inhibition of the expression of CDC42 gene, or negatively regulates the expression of PIAS3, an inhibitor of STAT3." (PMID 28718798, 2017). "Here, we found that extracellular VEGF bound to NRP1 in the cancer cell membrane, which activated Cdc42 to recruit intra-mitochondrial PHB to the front ends of CRC cells." (PMID 29100316, 2017). "CDC42 plays a key role in regulating actin dynamics and promotes the transendothelial migration of cancer cells." (PMID 28423712, 2017). "CDC42 is a small GTPase involved in multiple cellular functions whose aberrant expression or/and activity has been shown to be oncogenic in different cancer types." (PMID 28460460, 2017). "Complementary analyses using Ingenuity Pathway Analyses (IPA) identified “Cancer” as the most significant disease related term involving CDC42-dependent transcriptional deregulation." (PMID 28460460, 2017). "Our results establish that several cancer-related signaling pathways, including cell migration and cell proliferation, are regulated by CDC42." (PMID 28460460, 2017). "In keeping with a role of CDC42 in cancer onset and progression cellular growth, proliferation and cancer related pathways were significantly altered by modulation of CDC42 levels." (PMID 28460460, 2017). "For instance, cell division control protein 42 homolog (CDC42), a member of the Rho GTPase family, is known to facilitate tumorigenesis and cancer progression." (PMID 28820498, 2017). "We next investigated the effect of CDC42 on metformin response and cancer cell proliferation using both MTS assay and BrdU labeling." (PMID 28423712, 2017). "CDC42 was initially thought to be oncogenic in several cancer types via contributing to cell proliferation, survival, migration and invasion." (PMID 28871124, 2017). "The change of the KRAS protein, which was the prime therapeutic target for diverse human cancers, will induce the alteration of many key molecules of downstream signaling pathways including Ras-Ral-CDC42." (PMID 27769041, 2016). "CDC42, a Rho family GTPase, also plays an important role in various cancers and promotes proliferation and metastasis." (PMID 27613829, 2016). "Analysis of gene expression data from the SAGE database reveals changes in Cdc42 levels in cancer tissue, both increased and decreased, compared to normal tissue." (PMID 27104658, 2016). "Among these was IQ-domain GTPase-activating protein 1 (IQGAP1), a scaffold protein known to bind to Cdc42 and influence cell migration in normal and cancer cells." (PMID 27486972, 2016). "Ect2, which has activity for multiple members of the Rho GTPase family including RhoA, Rac1 and Cdc42, has been recognized as an oncogene in human cancer since 2010, being aberrantly overexpressed and mislocalised in various types of tumors." (PMID 27104658, 2016). "Increased expression of CDC42 is found in cervical (pre)cancers and was shown to promote formation of filopodia/pseudopodia thereby facilitating migration, a phenotype associated with anchorage independence as well." (PMID 27270309, 2016). "The molecular mechanism by which vertebrate Cdc42 stimulates invadopodia formation in cancer cell lines is poorly understood." (PMID 26765257, 2016). "Due to the key regulatory role of Cdc42 in actin cytoskeletal dynamics, many studies have demonstrated its importance in mediating tumor aggression, and propose it a promising target of cancer therapy." (PMID 27923383, 2016).
cancer (continued). "The fact that of the 10 rarely mutated genes, 5 (BCL2L1, CDC42, DDX5, AKT1 and APC) are listed in cancer gene databases indicates such association-based selection is useful." (PMID 27808240, 2016). "That CDC42 prompts cell motility has been reported in many types of human cancers, especially in CRC." (PMID 27923383, 2016). "Although Rac1/Cdc42 and RhoA have antagonistic functions, their coordination of their activities is essential for cell motility and cancer metastasis." (PMID 27384474, 2016). "In other cancer cell systems, it has been shown that the active form of Cdc42 is capable of binding to IQGAP1 to increase cancer migration and carcinogenesis." (PMID 27486972, 2016). "CDC42 was expressed in all samples with highest expression levels observed in cancer cell lines (P<0.028)." (PMID 26391404, 2015). "We previously showed that the reduced adhesion of Cdc42‐depleted cancer cells to ECs was due to decreased β1 integrin expression." (PMID 25677806, 2015). "It will be interesting to observe if RhoC or Cdc42 that we describe to be important for cancer cell: EC interaction give an advantage for their survival in the microenvironment surrounding the vessels." (PMID 25677806, 2015). "According to our in vitro functional assays, GIT1 regulates cancer cell mobility through Rac1/Cdc42 activation in NSCLC cells." (PMID 26462147, 2015). "Of particular interest for cancer metastasis, Cdc42-dependent, actin-based invadopodia are crucial for matrix degradation and invasion." (PMID 26558612, 2015). "The serine/threonine kinase PAK4 is a Cdc42 effector whose role is not well understood; overexpression of PAK4 has been associated with some cancers, and there are reports that correlate kinase level with increased cell migration in vitro." (PMID 26068882, 2015). "Cytoskeleton is associated with EMT and cytoskeletal reorganization is a prerequisite for cell motility and cancer cell invasion, and members of Rho GTPases including RhoA, Rac1 and Cdc42 play an important role in EMT as well." (PMID 26452029, 2015). "In summary, we show that simvastatin suppresses the SASP and its cancer-promoting effects by repressing Rac1 and Cdc42 activation." (PMID 26658759, 2015). "Among the targets of miR-29b, PI3K p85α and CDC42 have been shown to be closely related to cancer growth." (PMID 25622979, 2015). "This raises the possible correlations and importance between GIT1 and Rac1/Cdc42 in regulating cancer progression." (PMID 26462147, 2015). "P21-activated kinase 4 (PAK4), an effector of the Rho family protein Cdc42, is an important oncogene whose expression is increased in many human cancers and is generally positively correlated with advanced disease and decreased survival." (PMID 25975262, 2015). "With these five functional domains, IQGAP1 is able to bind Rac1 and Cdc42, β-catenin, E-cadherin, calmodulin and components of the mitogen-activated protein kinase pathway, all of which are involved in cancer development." (PMID 24763314, 2014). "Cdc42 plays a key role in cell motility as well as invasion and migration, which are targeted processes involved in cancer disease." (PMID 25360776, 2014). "In previous studies, this probe was successfully used to detect localized Cdc42 activation in cancer cells, T cells, and in the cortex of Xenopus oocytes during wound healing or polar body emission." (PMID 23384564, 2013). "Rac- and Cdc42-dependent functions for the Ras oncogene were first demonstrated in mammalian cancer cell lines in the late 1990s." (PMID 23950731, 2013). "Our studies on ML141 appear to offer the first demonstration that pharmacological inhibition of Cdc42 is of potential use in cancer treatment, at least in the context of enhancing response to other agents." (PMID 23606532, 2013).
cancer (continued). "Cdc42 is also crucial in the formation of filopodia, which are important in the motility of cancer cells." (PMID 24279335, 2013). "In this review, we focus on the trafficking and cancer-related functions of Cdc42, Rac1 and RhoA in mammalian cells." (PMID 23538840, 2013). "Cdc42 and Rac1 are also crucial in the formation of filopodia and lamellipodia, which are important in the invasion of cancer cells." (PMID 24040362, 2013). "It is well established that Cdc42, a member of the RhoGTPase family, positively regulates cancer cell migration." (PMID 23727359, 2013). "RhoA, RhoB and Cdc42 play a crucial role in the development of cancer, being main factors responsible for cellular motility and loss of adhesion." (PMID 23420497, 2013). "The Rac and Cdc42 pathways promote the uncontrolled proliferation, invasion and metastatic properties of human cancer cells." (PMID 24040362, 2013). "Active migration of tumor cells is a prerequisite for tumor progression and metastasis and reports show that EGF-induced cancer cell migration can be inhibited by suppressing Cdc42/Rac1 signaling pathways." (PMID 24040362, 2013). "The results presented here demonstrate an inhibition of cancer cell proliferation in vitro and in vivo following Rac1/Cdc42-inhibition." (PMID 24040362, 2013). "It has been demonstrated that Rho family small G proteins such as Rho, Rac, and Cdc42, and their regulatory molecules, such as RhoGAP, cooperatively control cellular motility in both normal and cancer cells." (PMID 24386239, 2013). "It has been shown that the expression of MMPs was regulated by small Rho GTPases (Cdc42, Rac1 and RhoA), which are involved in many normal and pathological cellular processes, including cancer invasion and metastasis." (PMID 22610942, 2012). "Among up-regulated miRNAs, miR-330 regulates CD44 and CDC42 and thus modulates tumourigenesis and angiogenesis in cancer." (PMID 22050707, 2012). "ARHGAP19 is a member of a family of GTPase activating proteins, and other family members, 8, 9, 12 and 15, are expressed in several types of cancer and activate Cdc42, Rac1 or RhoA, small GTPases required for migration." (PMID 21501518, 2011). "Further work investigating Cdc42 interaction with APC and its mutants on SW480 cells will likely reveal novel insights into the biology and cancer-causing abilities of these proteins." (PMID 21311754, 2011). "In particular, the role of RhoA (Ras homolog gene family, member A), Rac1 (Ras-related C3 botulinum toxin substrate 1) and Cdc42 (cell division cycle 42) in cancer progression induced by each of the three oncogenes is described." (PMID 21943101, 2011). "This analysis, allowed us to identify a highly significant group of 29 genes whose level of expression was significantly mediated by Rac1 and/or Cdc42 activity, only 14 of which have previously been reported to play a role in cancer." (PMID 20067638, 2010). "Microarray analysis revealed that the expression of 29 genes was dependent on Rac1 and Cdc42, many of which are known to play a role in cancer." (PMID 20067638, 2010). "Notably, strategies targeting Rho family-controlled pathways, including those focusing on CDC42, have garnered attention in cancer treatment, infectious diseases, and neurodegeneration." (PMID 41169985, 2025). "Notably, enhanced membrane-bound MMP14 expression promotes cancer cell invasion via cdc42 activation." (PMID 40134439, 2025). "GTPases, Ras, MAPK, PI3K, Cdc42 pathways), promoting cancer progression." (PMID 38535967, 2024).
cancer (continued). "The closely related DOCK11 and DOCK10, belonging to the same subfamily, exhibit 66% identity and 83% similarity in the DHR2 domain, suggesting their potential involvement in promoting cancer cell migration and infiltration through the activation of CDC42 or other GTPases." (PMID 38793626, 2024). "For example, inhibition of the interaction of cancer cells with pericytes by suppressing CD44 and CDC42 could induce cancer cells to develop another tumor growth pattern and has enhanced the anti-tumor immune response." (PMID 38255995, 2024). "Additionally, the association between elevated circulating CDC42 levels and adverse clinical outcomes underscores its potential as a prognostic marker in CRC, emphasizing its importance in both cancer biology and immune regulation." (PMID 38646539, 2024). "Moreover, Cdc42’s significance transcends cancer cell biology, playing a crucial role in maintaining the equilibrium and stability of Treg cells." (PMID 38646539, 2024). "Moreover, the transcripts of the following notional cancer genes were significantly increased: Rbl1, Bcl2l11, Map3k2, Bcl6, Ppp1, Cdc42, and Ppp2." (PMID 38731901, 2024). "Similarly, miR-195 has been shown to impede angiogenesis by targeting proteins such as VEGF, Vav guanine-nucleotide exchange factor 2 (VAV2), and cell division cycle 42 (CDC42), ubiquitously involved in cancer progression, including HCC." (PMID 37958352, 2023). "In our program to develop Rac/Cdc42 inhibitors as anti-metastatic cancer agents, we first characterized EHop-016, which inhibits Rac activation by the GEF Vav with a half maximal inhibitory concentration (IC50) of 1 μM and inhibits tumor growth and metastasis in mouse models." (PMID 37397366, 2023). "Since hAM preparations strongly reduced the migration of cancer urothelial cells, we further investigated their effect on the expression of key components required for efficient cell migration, such as cortactin, RhoA, RhoC, Cdc42 and Rac1." (PMID 37932474, 2023). "In the next step, we tried to further investigated the role of CDC42 in the pathophysiology of HPV-related cancer, including investigating the DMPs of CDC42, the difference of CDC42 expression in tumor and normal tissue, in HPV-pos and HPV-neg samples, respectively." (PMID 36936942, 2023). "CDC42 is involved in many crucial signaling pathways in cancer cells." (PMID 36812247, 2023). "Whether the novel Rac and Cdc42 inhibitors, developed by our group, affect leukocyte migration and function, especially during cancer development, remains to be determined." (PMID 37397366, 2023). "Also, we will determine the effective concentrations for Rac/Cdc42 inhibitors to impair cancer cell and protumorigenic cell migration in the TME, while preserving the function of anti-tumor immune cells." (PMID 37397366, 2023). "The identification of P-Rex1 as a NRBP1 binding partner sheds new light on the oncogenic role of NRBP1, not only due to the well-established roles of Rac1/Cdc42 in human cancer, but also because P-Rex1 has recently emerged as an important oncogene in its own right." (PMID 36693952, 2023). "The pharmacological role of Ketorolac in cancer is best viewed through two distinct classes of targets COX and Rac-1/Cdc42, which may contribute to the anti-inflammatory and anti-cancer activity." (PMID 37024613, 2023). "Therefore, we withdrew the supplements to test the effect of EGF alone on the activity of RAC1 and CDC42 in these cells and compared the responses with those of the cancer cells." (PMID 37057894, 2023). "This discrepancy may be due to the different roles of CDC42 in polyp development and cancer progression." (PMID 37365287, 2023). "Suppression of invasion that was mediated by Cdc42 inlung cancer cells." (PMID 37191432, 2023). "Much is known about Rac1/cdc42 in cancers such as breast and pancreatic." (PMID 37908840, 2023). "We identified CDC42 as a pivotal gene in the pathophysiology of HPV-related cancers." (PMID 36936942, 2023).